FHIT (fragile histidine triad diadenosine triphosphatase)
Diseases named in the same sentence as FHIT in open-access papers (continued):
Sharing a sentence is not in itself a finding about the gene and the disease.
gastric cancer (continued). "FHIT deletions also frequently occur in lung cancer Fhit knockout mice develop gastric carcinomas and skin cancers." (PMID 29069730, 2017). "In the present study, we observed that FHIT expression was reduced in gastric cancers with or without its CNA, suggesting that gene dosage as well as other mechanisms regulate FHIT expression in gastric cancer." (PMID 26360582, 2015). "This study aimed to investigate the effect of eradication of H. pylori on the expression levels of FHIT, IL-8 and P73 in the gastric mucosa of first-degree relatives of gastric cancer patients." (PMID 25875960, 2015). "The fragile histidine triad (FHIT) gene, encompassing the FRA3B fragile site at chromosome 3p14.2, is a candidate tumour suppressor gene involved in a variety of tumours, including gastric carcinomas." (PMID 14760383, 2004). "Alterations and abnormal transcripts of the FHIT gene have been reported in a number of primary human tumours, including gastric carcinoma." (PMID 14760383, 2004). "FHIT expression might be employed as a good potential marker for favorable prognosis of gastric cancer patients, while it was the converse for its mRNA." (PMID 29296239, 2017). "Furthermore, a high frequency of promoter hypermethylation of FHIT (62%) is observed in gastric cancers." (PMID 26360582, 2015). "Eradication of H. pylori may lead to up-regulation FHIT expression and down-regulation IL-8 expression in first-degree relatives of gastric cancer." (PMID 25875960, 2015). "Down-regulation of FHIT and up-regulation of IL-8 may be involved in the pathogenesis of H. pylori infection in the first-degree relatives of gastric cancer patients." (PMID 25875960, 2015). "In this study, we show that H. pylori infection or family histories of gastric cancer may correlate with a down-regulation of the FHIT expression and up-regulation IL-8 expression levels in the gastric mucosa of patients with functional dyspepsia." (PMID 25875960, 2015). "In this study, we investigated the expression levels of FHIT, IL-8 and P73 in the gastric mucosa of patients with functional dyspepsia having first-degree relatives with gastric cancer, and also analyzed the effects of eradication of H. pylori on the expressions of FHIT, IL-8 and P73." (PMID 25875960, 2015). "Moreover, FHIT expression in gastric carcinoma is related to the type, grade, and stage of the tumor and FHIT is an independent predictor for cancer-specific/overall survival of patients with gastric cancer." (PMID 25875960, 2015). "In addition, FHIT protein deficiency resulted in altered sensitivity to mitomycin C, UVC, and ionizing radiation in human gastric carcinoma cells in clonogenic assays." (PMID 24757411, 2014). "Aberrant transcripts of the FHIT locus were found in approximately 50% of esophageal, stomach and colon carcinomas, and loss of heterozygosity (LOH) at FHIT was found in 85% of primary effusion lymphoma, and 84% of gastric cancer." (PMID 23109895, 2012). "FHIT expression was negatively with depth of invasion, lymph node metastasis, distant metastasis, TNM staging and dedifferentiation of gastric cancer (p < 0.05)." (PMID 29296239, 2017). "In TCGA data, FHIT mRNA expression was not correlated with any clinicopathological parameter of gastric cancer (p > 0.05, data not shown)." (PMID 29296239, 2017). "Our data also show that FHIT is significantly decreased in first-degree relatives of gastric cancer compared with those without such relatives." (PMID 25875960, 2015). "Primary gastric carcinomas represent a rearrangement of the FHIT gene and 20 of 30 (67%) samples exhibited an absence of FHIT protein expression." (PMID 26360582, 2015).
colorectal cancer (12 papers, 1999 to 2022). A primary or metastatic malignant neoplasm that affects the colon or rectum. "FHIT, located on 3p14.2, controls apoptosis as a tumor suppressor, where deletions of FHIT appear more prevalent with advancing colorectal cancer stage." (PMID 35565354, 2022). "Finally, we demonstrated that depletion of FHIT significantly blocked TSA’s pro-apoptotic function in colorectal cancer HCT116 cells." (PMID 34108553, 2021). "This locus encodes FHIT, a candidate tumor suppressor and apoptotic regulator in colorectal cancer, and the higher frequency of deletion in stage III tumors suggests that loss of FHIT function may contribute to the progression of colon cancer from a lower to higher stage disease." (PMID 22860045, 2012). "The main aim of the study is to assess expression levels of CDH1, FHIT, PTEN, and TTPAL genes in tumors and peripheral bloods of colorectal cancer patients in staged I–IV." (PMID 36161592, 2022). "The presented study analysed the expression of CDH1, PTEN, FHIT, and TTPAL genes using tissue samples and blood of patients with different stages of colorectal cancer (CRC)." (PMID 36161592, 2022). "Although related expression levels in tissue did not correlate with its expression in blood, consistent with previous studies FHIT and TTPAL genes upregulation and CDH1 downregulation, in especially tumoral tissues, may serve as predictive determinants for the patients with colorectal cancer." (PMID 36161592, 2022).
colon carcinoma (11 papers, 2003 to 2025). "CCSER1, along with other genes like FHIT, was found to play a significant role in genome stability and the cell division of colon cancer." (PMID 40870036, 2025). "FHIT methylation has been identified in various types of cancer, including colon cancer; to the best of our knowledge, this is the first report implicating aberrant DNA hypermethylation of FHIT in IBD pathogenesis." (PMID 32375395, 2020). "In colon cancer cell lines, deletions affected FHIT in over 60% of the cell lines compared to 9% of primary tumors." (PMID 23805207, 2013). "When the FHIT locus was first discovered, we noted frequent homozygous deletions in colon cancer cell lines and aberrant RT–PCR products in primary colorectal cancers." (PMID 12771912, 2003). "It is worth noting that mutations in the tumor suppressor genes, FHIT and WWOX, which are located within FRA3B and FRA16D CFS, respectively, due to unresolved TRC-induced CFS instabilities have been observed at a high frequency in gastric and colon cancer." (PMID 37626846, 2023). "FHIT gene expression in colon cancer was investigated by various methods in colon cancer." (PMID 36161592, 2022). "A study from United Kingdom has shown reduced expression of FHIT in a small proportion of colonic precancerous lesions and in increased proportions of primary and metastatic colorectal cancers suggesting that FHIT plays a role in the development and progression of some colon carcinomas." (PMID 23573237, 2013). "However, studies related FHIT gene for colon cancer tumorigenesis are limited." (PMID 36161592, 2022). "Specifically, we targeted large genes PRKG1, NEGR1, and MAGI2 in fibroblast line UM-HF1 (HF1) and FHIT and WWOX in lymphoblastoid line GM12878 and colon cancer line HCT116 as model systems for replication stress-associated SV formation." (PMID 39505880, 2024). "Interestingly, we found that colon tumors were by far the most frequently affected by focal deletions in CFS-like genes, with deletion frequencies as high as 21% for A2BP1, 17% for MACROD2, 9% for FHIT and 9% for PARK2." (PMID 23805207, 2013).
non-small cell lung carcinoma (11 papers, 2004 to 2024). A group of at least three distinct histological types of lung cancer, including non-small cell squamous cell carcinoma, adenocarcinoma, and large cell carcinoma. "FHIT loss was observed in 64% of non-small-cell lung cancer patients and was significantly associated with squamous cell carcinoma and poor tumor grade." (PMID 28036263, 2017). "Emerging evidence indicates that FHIT is a candidate tumor suppressor in non-small cell lung cancer (NSCLC)." (PMID 26796853, 2016). "In conclusion, we identified significant associations between seven genes (CDKN2A, RASSF1, MGMT, RARB, DAPK, WIF1 and FHIT) and smoking behavior in non-small cell lung cancer patients." (PMID 25754026, 2015). "Using in vivo and in vitro models, we show the ability of FHIT to inhibit metastasis and EMT through the suppression of metastasis-related and EMT-associated genes including MTDH, HMGA2, VIM, FN1, CDH1 and Snail in non-small-cell lung cancer (NSCLC) cells." (PMID 25340791, 2014). "The fragile histidine triad (FHIT) gene, encompassing the FRA3B fragile site at chromosome 3p14.2, is a tumour suppressor gene involved in different tumour types including non-small-cell lung cancers (NSCLCs)." (PMID 15150628, 2004). "However, in non-small cell lung carcinoma (H460) lacking FHIT, FHIT expression reduces doxorubicin and etoposide-induced cytotoxicity." (PMID 31089360, 2019).
pancreatic cancer (10 papers, 2002 to 2025). "Exogenous expression of FHIT in human pancreatic cancer cells causes cell cycle arrest and apoptosis and loss of full length transcripts is frequent in primary pancreatic cancers of humans (62%) and BOP-treated hamsters (73%)." (PMID 24212630, 2011). "Recently, studies revealed that the adenoviral overexpression of FHIT in human pancreatic cancer cells effectively suppressed cell growth and induced caspase-dependent apoptosis in both in vitro and in vivo experiments." (PMID 24757411, 2014). "FHIT gene is a putative tumor suppressor gene located at chromosome 3p14, which is expressed in normal pancreatic ductular cells and is altered in pancreatic cancers." (PMID 24212630, 2011). "The fragile histidine triad (FHIT) gene, a tumour suppressor, is lost in most malignancies, including pancreatic cancer." (PMID 20664591, 2010). "Furthermore, introduction of FHIT into pancreatic cancer cells, from which most FHIT had been deleted, induced apoptosis, delayed tumor growth, and prolonged survival in a mouse model." (PMID 38069335, 2023). "A germline intronic deletion in FHIT has also been identified in a pancreatic cancer study." (PMID 24955146, 2014). "FHIT was identified as a protective factor for pancreatic cancer via Mendelian randomization, showing a significant negative correlation with CHST11 in TCGA (R = -0.23) and lower expression in naïve T cell_ CHST11pos than in naïve T cell_ CHST11neg." (PMID 41346619, 2025). "In addition, it was previously observed that frequent human pancreatic cancers and cell lines with high MSI had homozygous deletions within FHIT." (PMID 14760383, 2004). "In addition, it was previously observed that human pancreatic cancers and cell lines with high MSI frequently had homozygous deletions within FHIT." (PMID 12177781, 2002).
squamous cell carcinoma (8 papers, 1999 to 2021). A carcinoma arising from squamous epithelial cells. "Loss of heterozygosity (LOH) at the FHIT gene locus in adenocarcinoma was less frequent than that in squamous cell carcinoma." (PMID 12865924, 2003). "The FHIT gene loss was observed in 64% of NSCLC patients and is reported to be significantly associate with squamous cell carcinoma and poor tumor grade." (PMID 28036263, 2017). "In conclusion, this study showed for the first time that FHIT gene alteration is a very frequent event in both squamous cell carcinomas and adenocarcinomas of the lung despite whatever the smoking status." (PMID 15150628, 2004). "It was found that in 2,616 coding genes, 2 or more integration sites presented among samples, like RAD51B, MACROD2, FHIT, CSMD1, LRP1B, and DLG2, which had already been previously reported as frequent sites of integration in squamous carcinoma samples." (PMID 33810183, 2021).
hepatocellular carcinoma (7 papers, 1998 to 2021). A malignant tumor that arises from hepatocytes. "Loss of FHIT expression is commonly associated with hypermethylation of the gene, and frequent FHIT hypermethylation has been reported in hepatocellular carcinomas, and in carcinomas of the larynx, breast, lung, cervix, vulva, and kidney." (PMID 25024751, 2014). "While loss of FHIT expression can occur due to chromosome breaks, FHIT is also highly methylated in solid tumors, such as lung, breast, bladder, prostate, cervical, esophageal, and hepatocellular cancers." (PMID 34092254, 2021). "The purpose of the present study was to examine the expression and function of FHIT in human hepatoma cells." (PMID 24396396, 2014). "In order to directly show that FHIT acts as a tumor-suppressor gene in hepatoma cells, the wild-type FHIT was generated and incorporated into an N′-terminal HA-tagged FHIT plasmid." (PMID 24396396, 2014). "The aim of this study was to investigate the methylation status of fragile histidine triad (FHIT) and the effects of FHIT on cell growth and cyclin D1 expression in hepatoma cells." (PMID 24396396, 2014). "The total proteins from the human hepatoma cell lines HepG2, Hep3B and Huh7 were collected and the expression levels of FHIT were analyzed." (PMID 24396396, 2014). "The methylation status in the promoter region of FHIT in the hepatoma cells was measured using methylation-specific polymerase chain reaction (PCR)." (PMID 24396396, 2014). "However, the methylation status of FHIT in human hepatoma cells requires further investigation." (PMID 24396396, 2014).
leukemia (7 papers, 2013 to 2024). A malignant (clonal) hematologic disorder, involving hematopoietic stem cells and characterized by the presence of primitive or atypical myeloid or lymphoid cells in the bone marrow and the blood. "In ALL, loss of FHIT expression causes inactivation of FHIT protein that may result in the development of leukemias." (PMID 38587694, 2024). "In addition, three integration sites of the RV vector were found within cancer-related genes (Klf5, NUMB, and FHIT), all of which are associated with leukemogenesis or leukemia progression." (PMID 23990961, 2013). "Given that FHIT is found methylated in a small percentage of cells derived from PBMCs, there is a possibility that prior FHIT methylation may predispose individuals to leukemia/lymphomas." (PMID 35663592, 2021). "Promoter DNA methylation, an epigenetic modification is notably seen to contribute to the development of leukemia as confirmed in case of FHIT gene in various forms of cancers and in particular ALL." (PMID 38587694, 2024). "This also signifies the diverse role of FHIT in different types of leukemia." (PMID 38587694, 2024). "Interestingly, FHIT was also successfully used as a therapeutic gene in cancer cell lines, where it triggers apoptosis, and several preclinical models of FHIT-null cancer, including lung, esophagus, pancreas, breast and leukemia." (PMID 24223161, 2013). "The frequent alteration in particular reduction in FHIT expression as found in this study in ALL and other quoted studies gives an evidence that inactivating changes at the FHIT locus could supplement for the development to leukemia’s." (PMID 38587694, 2024). "Furthermore, FHIT restoration in FHIT-negative cancer cells of both epithelial origin and leukemias blocks in vivo tumor formation and triggers caspase-mediated apoptosis." (PMID 27166255, 2016).
lung adenocarcinoma (7 papers, 1998 to 2023). A carcinoma that arises from the lung and is characterized by the presence of malignant glandular epithelial cells. "When genomic sequences from lung adenocarcinomas were stratified by A3B and FHIT expression, those with high A3B and FHIT loss showed significantly higher A3 signature mutation loads than high A3B expressers with normal FHIT levels." (PMID 33292100, 2020). "FHIT alterations and loss of expression occur more frequently in precancerous lung tissues of smokers, such that lung adenocarcinomas would show FHIT loss unrelated to age at diagnosis." (PMID 29254236, 2017). "Interestingly, C > A mutations were also enriched in A3B-high/FHIT-low lung adenocarcinomas." (PMID 25401976, 2015). "Data from lung adenocarcinoma patients showed that FHIT expression is positively correlated with LINC00173 and negatively correlated with SNAIL." (PMID 38069335, 2023). "This raises the question of what triggers the suppression of FHIT expression in human lung adenocarcinoma." (PMID 38069335, 2023). "This is consistent with previous reports showing that LINC00173 and FHIT act as tumor suppressors in lung adenocarcinoma." (PMID 38069335, 2023). "Our results using human lung adenocarcinoma samples are consistent with this because a significant positive correlation was observed between lower expression of FHIT and worse prognosis." (PMID 38069335, 2023). "In this study, we propose a model in which LINC00173 positively regulates FHIT expression by repressing SNAIL function in human lung adenocarcinoma." (PMID 38069335, 2023). "Using data from The Cancer Genome Atlas (TCGA), we show that FHIT-low/APOBEC3B-high expressing lung adenocarcinomas display significantly increased numbers of APOBEC signature mutations." (PMID 25401976, 2015). "Taken together, we propose that LINC00173 positively regulates FHIT gene expression by binding to SNAIL and inhibiting its function in human lung adenocarcinoma." (PMID 38069335, 2023). "Data from 501 patients with lung adenocarcinoma also support the existence of a LINC00173-SNAIL-FHIT axis, as FHIT expression correlated positively with LINC00173 (p = 1.75 × 10−6) and negatively with SNAIL (p = 7.00 × 10−5)." (PMID 38069335, 2023). "Although the detection of FHIT may be sufficient for prognosis, the expression status and genetic defects of LINC00173 in pre-cancerous or actual lung adenocarcinoma may also be a potential biomarker for carcinogenesis and progression of lung adenocarcinoma." (PMID 38069335, 2023).